KRAS (KRas proto-oncogene, GTPase)
Diseases named in the same sentence as KRAS in open-access papers (continued):
Sharing a sentence is not in itself a finding about the gene and the disease.
tumor (continued). "The integrin αvβ3 regulates tumour initiation, anchorage independence, self-renewal and erlotinib resistance by activating the KRAS-RalB-NF-κB pathway." (PMID 26792023, 2016). "Among all the 702 hotspots, we found that 68 were highly prevalent in one tumor type, 11 in two tumor types, 2 (KRAS G12 and PIK3CA E542) in three tumor types, and 1 (KRAS G13) in four tumor types." (PMID 27356755, 2016). "In contrast, all seven EGFR-mutated tumours had lower ZEB1 and the levels of ZEB1 were significantly lower in EGFR mutant tumours than that in EGFR wild-type tumours (Student's t-test P=0.027) or in KRAS mutant tumours (Student's t-test P=0.013)." (PMID 27456471, 2016). "Multiple KRAS and NRAS codon 12 and 13 microclonal mutations significantly co-occurred within tumor samples (p=4.8×10−4), suggesting ongoing formation of and selection for Ras-activating mutations." (PMID 27683039, 2016). "We were able to demonstrate that both differences in mutation and differences in selection drive variation in the distribution of KRAS driver substitutions between tumor types." (PMID 26902163, 2016). "We found that the presence of those KRAS driver substitutions that we predicted as favored by selection in only one tumor type correlated significantly with higher tumor stage, within that type of tumor." (PMID 26902163, 2016). "Pooled HR was 1.57 for DFS (95% CI 1.17-2.09, p=0.002), indicating an increased hazard for disease recurrence after tumor resection for KRAS mutant patients." (PMID 26840022, 2016). "In the case of CRC, texture features have been shown to correlate with KRAS expression, patient’s survival, tumour staging, and tumour response." (PMID 27136925, 2016). "Using heterocellular multivariate phosphoproteomics, we demonstrate how oncogenic KRAS signals through local non-tumor cells to achieve a differential reciprocal signaling state in the inceptive tumor cells." (PMID 27087446, 2016). "Our data suggests that oncogenic KRAS in tumor cells establishes a reciprocal signaling axis between stromal cells and tumor cells." (PMID 27087446, 2016). "Overall, a rechallenge with anti-EGFR agents was observed in 52 patients with presumably KRAS wild-type tumours." (PMID 27389564, 2016). "In most Oncomine data sets with lower tumour ZEB1, the expression levels of both EGFR and KRAS were marginally higher in tumours compared with paired normal lung tissues." (PMID 27456471, 2016). "Data were analysed by tumour RAS (KRAS/NRAS) and BRAF status, and baseline amphiregulin (AREG) expression." (PMID 27764839, 2016). "In contrast, mutational activation of KRAS cannot initiate cancer in vivo, and only when combined with a mutation in APC mutant KRAS does promote tumor progression." (PMID 27276710, 2016). "KRAS is one of the most frequently activated oncogenic drivers in cancer and is mutated in >90% of PDA tumor cells." (PMID 27087446, 2016). "Some KRAS drivers seem to be more positively selected across tumor types, while others are strongly favored only in particular tumor types." (PMID 26902163, 2016). "While some KRAS driver substitutions appear to be highly favored by natural selection across tumor types, some are highly favored only within specific types of tumors." (PMID 26902163, 2016). "Many miRNAs targeting the KRAS oncogene were found to be down-regulated in human cancers, acting as tumor suppressors." (PMID 26646588, 2016). "Complete RAS data were available for 143 of 150 patients, of whom 69 (45%) had RAS WT tumours (i.e., WT for exons 2, 3 and 4 of both KRAS and NRAS)." (PMID 27764839, 2016). "Enhanced inhibition of tumor differentiation and progression by rapamycin was demonstrated to be specifically dependent on loss of PTEN in KRAS-mutant mice (KC)." (PMID 27200288, 2016).
tumor (continued). "The discrepancy observed in some samples when using the SNaPshotTM assay was due to insufficient sensitivity of this technique upon massive tumor regression by CRT as application of the therascreen® KRAS test revealed concordant results." (PMID 27064574, 2016). "Our findings reveal a novel function of oncogenic KRAS in regulating accurate mitotic progression and suggest new avenues to therapeutically target KRAS-mutant tumours and stratify patients in ongoing clinical trials of anti-mitotic drugs." (PMID 27412232, 2016). "We characterized JQ1 in a panel of KRAS mutant NSCLC cell lines for its anti-tumor activity as well as its effect on c-Myc expression." (PMID 27607580, 2016). "The study also reported a rate of HER2 amplification in KRAS WT tumours of just over 5%, consistent with our findings of 5.2%." (PMID 26690310, 2016). "We therefore sequenced the genomic region of the KRAS gene that encompasses the most frequently mutated codons, i.e. codons 12 and 13, in the MSI+ tumours of our panel." (PMID 26298837, 2016). "In combination with chemotherapy, these therapies are the only approved biomarker-driven therapies currently licensed for treatment of CRC and have extended survival up to 41.3 months in patients with tumours wild type (WT) for KRAS and NRAS." (PMID 27340376, 2016). "In conclusion, KRAS mutation in CRC leads to decreased expression of RCAN2, resulting in tumor proliferation by derepression of the calcineurin–NFAT signaling pathway." (PMID 27526107, 2016). "In xenograft model, zoledronic acid significantly reduced the weight of wild type KRAS-EGFR-expressing xenograft tumor by decreasing the proliferative capacity." (PMID 27780929, 2016). "This was discovered using parallel siRNA screens in KRAS mutant and wild type colorectal isogenic tumour cells and subsequently validated in a genetically diverse panel of 26 colorectal and pancreatic tumour cell models." (PMID 26881434, 2016). "Specifically, KRAS, PIK3CA and KIT mutations were detected in 31/48 (64.6%), 11/48 (22.9%), 8/48 (16.7%) tumor specimens, respectively." (PMID 26968814, 2016). "Conversely, tumor suppressive miRNAs, such as let-7 and miR-34, have been found to repress the expression of oncogenes, such as KRAS." (PMID 26646588, 2016). "Mutant KRAS dramatically affects the composition of the exosome proteome in CRC: exosomes from mutant KRAS cells contain many tumor-promoting proteins, including KRAS27." (PMID 27312428, 2016). "Retrospectively, the pyrogram from the whole tumor actually reflects the overlap of KRAS G12C and G12D pyrograms." (PMID 27597976, 2016). "In this report, we reveal a previously unidentified tumor cell-autonomous role of KRAS(G12D)-induced CXCR2 signaling in mediating growth of neoplastic PDAC cells." (PMID 26771140, 2016). "KLF2, an member of KLF family with Cys2/His2 zinc-finger domains, is diminished in multiple cancers and possesses tumor-suppressor features such as inhibition of cell proliferation mediated by KRAS." (PMID 26840083, 2016). "Injection of mutant-KRAS mRNA induces tumor-like structures with many documented similarities to tumors, in Xenopus tadpoles." (PMID 26988909, 2016). "For nine patients in the cohort, mutational analyses for KRAS, BRAF, and PIK3CA hotspots were available for matched tumor tissue, CTCs, and ctDNA." (PMID 27863403, 2016). "Our results strongly indicated that tumour cells and xenografts with activated KRAS relied on suppressing p21 activity for growth." (PMID 27193833, 2016). "When mutant KRAS co-exists with mutant PIK3CA in the same tumor, the protein levels of autophagic factor LC3 are recorded high." (PMID 26802026, 2016). "Most patients receive regimens that include a combination of these key drugs, and cetuximab or panitumumab are applied if the tumor has wild-type KRAS as well as NRAS." (PMID 27166185, 2016). "It is important to remember that other oncogenes have dual functions as tumour suppressors and oncogenes including KRAS and MYC." (PMID 27322327, 2016).
tumor (continued). "Clinical outcome was better in patients with KRAS exon 2 wild type (median OS 30.0 months (23.0–NA); median PFS 12.0 (8.0–20.0)), compared with KRAS exon 2 mutant tumours (median OS 7.0 months (5.0–37.0); median PFS 7.0 (4.0–18.0))." (PMID 26766738, 2016). "For example, the frequent KRAS mutation in CRC cells leads to inactivation of STAT1 and subsequent insensitivity of tumor cells to the anti-tumorigenic effects of IFN-γ." (PMID 26938566, 2016). "We also assessed the anti-tumour effect of AZD5438 on human tumour xenografts to access the KRAS selectivity of this compound in an in vivo setting." (PMID 26881434, 2016). "By tNGS primary tumours were RAS wildtype in 5/14 and mutated in 9/14 (8/9 KRAS exon 2; 1/9 NRAS Exon 3) of cases." (PMID 27756406, 2016). "Stromal accumulation is KRAS driven and is initiated in PanIN lesions, suggesting that its early onset is important to tumor growth and progression." (PMID 27096871, 2016). "KRAS, NRAS and BRAF mutations were detected in two or all three tumor types while mutations in EGFR were uniquely detected in NSCLC." (PMID 27101000, 2016). "Our analysis demonstrated that both mutational biases and differences in the manner in which natural selection affects various KRAS driver substitutions contribute to determining the distribution of KRAS driver substitutions within a tumor type." (PMID 26902163, 2016). "Following immunohistochemical staining showed that HOC-7 and HOC-7 IĸBαM tumor tissues expressing KRAS strongly due to persistent activity of KRAS/MAPKs pathway, which confirm the KRAS mutation." (PMID 27484466, 2016). "MiR-27a bound to KRAS mRNA and inhibited its translation, acting as a tumor suppressor through inhibition of the RAS-MAPK pathway." (PMID 26646588, 2016). "Nevertheless, every preclinical model has inherent “tumor heterogeneity” issue since not all of the cells are 100% tumor cells or from the same clone of tumor (i.e. KRAS G12D tumor cell vs coexistent PIK3CA E542K tumor cell in the same tumor)." (PMID 26909603, 2016). "Several independent studies have indicated that let-7 members act as tumor suppressors on various tumor types by targeting KRAS and HMGA2 oncogenes." (PMID 26701848, 2016). "Here, we demonstrate that SIRT2 functions as a tumor suppressor in the context of KRAS-dependent tumorigenesis." (PMID 27637077, 2016). "The ctDNA carries the same somatic alterations as the tumor itself and can be used to detect clinically relevant mutations such as those in the epidermal growth factor (EGFR) or KRAS genes." (PMID 28066769, 2016). "HER2‐amplification/overexpression is identifiable by immunohistochemistry, occurring infrequently in stage II–III CRC, rising in stage IV and further in KRAS/BRAFWT tumours." (PMID 26690310, 2016). "Taken together, our findings provide evidence supporting the role of miR-16 as a tumor suppressor in CRC by targeting KRAS." (PMID 27857191, 2016). "Age and tumor stage were adjusted for in the multivariate analysis of most studies, but BRAF mutation, KRAS mutation, and microsatellite instability (MSI) were assessed as confounding variables only in a few studies." (PMID 26941852, 2016). "We therefore aimed to assess the KRAS status in multiple pre-therapeutic biopsies as well as in resected tumor specimens." (PMID 27064574, 2016). "Two datasets were used to analyze the distribution of KRAS codon 12 and 13 driver substitutions within these tumor types." (PMID 26902163, 2016).
tumor (continued). "Our results demonstrated that long-term exposure of NSCLC cells to erlotinib results in the acquisition of tumor phenotypic features associated with EMT, a phenomenon that was more prominent with KRAS-mutated cell lines." (PMID 27248176, 2016). "Allograft tumours derived from APC/KRAS/PTEN spheres were also sensitive to sequential treatment: strikingly, three of five allograft tumours showed regression in response to 0.01 mg kg−1 bortezomib followed by BEZ235." (PMID 27897178, 2016). "Concomitant blockage of these two key pathways is thus largely accountable for enhanced chemosensitivity observed in let-7b-transfected KRAS mutant tumor cells." (PMID 25946136, 2015). "This is most likely due to the fact that we performed macro dissection of the tissue in order to obtain tumor DNA and PDAC tumors contain a high proportion of stromal tissue and thus we will ultimately have contaminating non-tumor KRAS WT cells in the sample." (PMID 26498594, 2015). "Further, the mechanism in which miR-200c exerts its tumor suppressive function is by targeting KRAS." (PMID 26392416, 2015). "Confirmed response rates were 44.4% in patients with wild-type KRAS tumours and 37.1% in those with mutant KRAS tumours (P >0.05)." (PMID 25925749, 2015). "In contrast in another study, a more targeted identification of oncologists treating mCRC found that in 2010 all oncologists (34/34) tested tumor KRAS status." (PMID 26491871, 2015). "We found that let-7b repletion selectively sensitized KRAS mutant tumor cells to the cytotoxicity of paclitaxel and gemcitabine." (PMID 25946136, 2015). "We previously demonstrated that the C118S mutation reduced the ability of wild-type HRAS to be activated in an eNOS-dependent fashion and to promote oncogenic KRAS-driven tumor growth." (PMID 25902334, 2015). "In this study, we also investigated EGFR mutation, KRAS mutation and ALK-IHC in the 14 patients with PPC whose tumor specimens were available." (PMID 26682906, 2015). "Because the in vitro and in vivo systems showed striking differences in the effect of KRAS mutation on PI sensitivity, we explored metabolic differences, a facet of RAS signaling which would be heavily influenced by the tumor environment." (PMID 26709701, 2015). "The OR for dissemination for BRAF mutated tumours is low both in MSS tumours and in KRAS wild type tumours; however these results are statistically non-significant." (PMID 25884297, 2015). "The finding that let-7b repletion sensitized KRAS mutant tumor cells to both drugs suggests that in addition to the shared molecular targets, let-7 possibly also modulates other signaling molecules that synergize specifically with each drug." (PMID 25946136, 2015). "The LCM-RPPA workflow here described provided us with clear and uncontaminated information on the KRAS signaling network of tumor epithelium." (PMID 26468985, 2015). "In the current study, we uncovered a new role of let-7b as a chemosensitizer in drug-naive KRAS mutant tumor cells." (PMID 25946136, 2015). "MiR-802 is the third most significantly repressed miRNA in PDAC, besides the tumor suppressor miRNAs miR-216 and miR-217 that - among others - target KRAS, PTEN, and SMAD7." (PMID 25910082, 2015). "Evidence from other reports supported the idea that KRAS mutation and MMR status are genetic markers that arise early and remain biologically relevant throughout all stages of tumor progression." (PMID 26042813, 2015).
tumor (continued). "These authors published a case report of a mCRC patient with a KRAS wild-type primary tumor and synchronous metastases evaluated before beginning treatment with cetuximab." (PMID 26318427, 2015). "Almost all (97.7%; 294/301) oncologists were aware of all their patients’ tumor KRAS status prior to treatment with panitumumab." (PMID 26491871, 2015). "The identification of genes known to provide a selective advantage to cancer cells driven by mutant KRAS provides strong evidence of the ability of this approach to uncover gene combinations under selective pressure during tumor evolution." (PMID 26047463, 2015). "Mutations in these genes were almost exclusively identified in BRAF/KRAS/NRAS mutant tumours, suggestive of cooperative biological effects." (PMID 26506417, 2015). "Combined MEK/ERK and PI3K/AKT inhibition is required to effectively trigger apoptosis in KRAS mutant tumor cells." (PMID 25946136, 2015). "In the US, there was rapid uptake of KRAS tumor testing by 2010 in one study, with 97% of 1,188 patients with mCRC being tested in 2010 compared with 7% of patients being tested in 2006." (PMID 26491871, 2015). "Compared to KRAS wild-type cells, KRAS mutant tumor cells of the same tissue origin were shown to express notably higher KRAS mRNA and lower let-7b levels." (PMID 25946136, 2015). "In contrast to deficient MMR (dMMR) CRC, data on the presence of KRAS oncogenic mutations in proficient MMR (pMMR) CRC and their relationship with tumor progression are scarce." (PMID 26042813, 2015). "It appears that combination of prenylation inhibitors and PAK1 inhibitor adequately disrupt the signaling network downstream of KRAS and provide a prominent anti-tumor effect." (PMID 25956913, 2015). "Specifically, there was no statistical difference between KRAS-knockdown cells re-expressing Flag-KRASC118S and KRAS-knockdown cells with regards to tumor growth or tumor weight at endpoint." (PMID 25902334, 2015). "Whereas targeting mutant KRAS remained difficult, several studies demonstrated that NRAS mutations can be targeted by inhibition of MEK in tumor cell lines." (PMID 26544513, 2015). "The miniature biodegradable implant siG12D-LODERTM was inserted into a tumor and released a siRNA drug against KRAS(G12D) along four months." (PMID 26009994, 2015). "BRAF mutant allele frequencies were highly concordant with the KRAS and NRAS mutant allele frequencies, suggesting that concomitant mutations are present in the same tumor population." (PMID 26498038, 2015). "The miR-217 inhibits in vitro tumor cell growth and it functions as a potential tumor-suppressor by influencing the Akt/KRAS signaling pathway, therefore, miR-217 is frequently down-regulated in PDAC." (PMID 26499892, 2015). "The well-known mutual exclusiveness of KRAS and BRAF mutations was observed, and MSI was more prevalent in KRAS wild-type and BRAF mutated tumours." (PMID 25884297, 2015). "We therefore performed fluorescence in situ hybridization with probes binding to the genomic region of chromosome 12 harboring the KRAS gene on tumor samples from four patients with acquired resistance to crizotinib." (PMID 25691052, 2015). "In this analysis, tumor shrinkage was more pronounced in KRAS wild-type patients receiving chemotherapy plus cetuximab compared to those exposed to chemotherapy alone." (PMID 26308250, 2015). "All patients received platinum-doublet chemotherapy in the first-line setting with higher percentage of wild-type KRAS tumor patients receiving gemcitabine (57.1%) as compared to mutated tumor patients (37.9%)." (PMID 26416458, 2015). "The current assays for KRAS genotyping in tumor samples include direct sequencing of genomic DNA and PCR based assays." (PMID 25568935, 2015).